INS (insulin)
Diseases named in the same sentence as INS in open-access papers (continued):
Sharing a sentence is not in itself a finding about the gene and the disease.
Hyperglycemia (continued). "Further studies also revealed overexpression of hepatic miR-27a efficiently repressed HCD-initiated liver damage, hyperglycemia and hyperinsulinemia, indicating improved systemic glucose homeostasis and insulin sensitivity." (PMID 29101357, 2017). "Type 1 diabetes, resulting from the autoimmune destruction of insulin-producing β cells in the pancreas, is characterized by low level of insulin and hyperglycemia." (PMID 28790925, 2017). "Losses in infusion set actuation (LISAs) can adversely affect clinical outcomes, resulting in hyperglycemia due to impaired insulin delivery." (PMID 28098839, 2017). "Individuals with T2DM develop hyperglycemia due to their inability to secrete insulin or use insulin properly." (PMID 29209613, 2017). "Advanced glycation end products and progression of atherosclerosis can be caused by a complex combination of pathological pathways such as hyperglycemia itself, increased insulin resistance, inflammatory responses, and decreased fluidity of the cell membrane." (PMID 28178180, 2017). "Melatonin influences type 3 diabetes by 1) suppressing Aβ toxicity and tau hyperphosphorylation, 2) controlling insulin resistance and hyperglycemia, and 3) preventing hyperglycemia-induced BBB disruption." (PMID 28764741, 2017). "In one intriguing recent study, rats were rendered diabetic with streptozotocin injection; after 6 months of hyperglycemia, their glycemic control was markedly improved by daily administration of insulin for another 6 months." (PMID 28335416, 2017). "Emerging evidence indicates that the upregulation of the HO system and related products increases pancreatic beta cell insulin release and reduces hyperglycaemia in different animal models." (PMID 29081883, 2017). "Our recent in vivo investigation showed that F2 is the most effective subfraction with respect to the prevention of hyperglycemia, suppression of HbA1C, and improvement of insulin sensitivity (undergoing review)." (PMID 28715446, 2017). "Pharmacological inhibition of P300 acetyltransferase activity by a specific inhibitor improves insulin sensitivity and decreases hyperglycemia in obese mice." (PMID 28743992, 2017). "In such metabolic milieus, insulin fails to suppress hepatic gluconeogenesis despite the presence of hyperglycemia and the insulin-mediated glucose uptake into skeletal muscle is impaired." (PMID 28974008, 2017). "Long-acting analogs can maintain high GLP-1 levels and stimulate secretion of insulin for 24 h, even during fasting periods, resulting in a greater reduction in basal hyperglycemia." (PMID 28115994, 2017). "Ineffective secretion or action of insulin leading to persistent hyperglycaemia is known to induce cardiovascular damage via oxidative stress and inflammatory mechanisms." (PMID 29181404, 2017). "The agonists of PPARγ have been widely applied for the management of hyperglycemia in T2DM by its effects on insulin sensitivity and serum adiponectin increase, and adipocyte differentiation induction that often results in weight gain." (PMID 28399925, 2017). "The UK guideline also incorporates the new evidence to show that the continued use of long-acting basal insulin helps to prevent the rebound hyperglycemia seen when the intravenous insulin is stopped." (PMID 28364357, 2017). "Insulin is formulated as pharmaceutical products, particularly for management of hyperglycemia owing to imperfect insulin secretion." (PMID 28859155, 2017). "There are some theoretical explanations for the overrepresentation of skin changes in abnormal glucose metabolism; both hyperglycaemia and decreased insulin signal affect skin function." (PMID 28831117, 2017). "He presented hyperlipidemia and hyperglycemia; his β cells were still functioning and producing insulin, and his glucose levels in blood were close to normal values." (PMID 28116330, 2017).
Hyperglycemia (continued). "Insulin plus atorvastatin (combined) treatment effectively restored renal function as well as renal Oat3 function which correlated with the decrease in hyperglycemia and oxidative stress." (PMID 29051569, 2017). "There is growing consensus within the scientific community that the prolonged stimulation of insulin release from β-cells under conditions of chronic hyperglycemia contributes to their eventual demise." (PMID 28660193, 2017). "Reduced sensitivity to insulin in peripheral target tissues such as liver, muscle, and adipose tissue leading to abnormal insulin secretion, ultimately result in hyperglycemia." (PMID 28883792, 2017). "Next, we utilised osmotic mini-pumps to infuse streptozotocin (STZ; doses ranging 80–200 mg/kg) over the course of 14-days to decrease insulin-producing capacity thus promoting hyperglycemia." (PMID 29075006, 2017). "Excessive secretion of glucagon, a functional insulin antagonist, significantly contributes to hyperglycemia." (PMID 28775305, 2017). "T2D patients had fasting hyperglycaemia, lower total insulin secretion rate, and profoundly impaired beta-cell glucose sensitivity (ß-GS) compared with ND." (PMID 28827671, 2017). "During her second pregnancy with twins, she required up to 75 units of injected insulin to control her postprandial hyperglycemia and occasionally experienced hypoglycemia." (PMID 29142885, 2017). "The increased insulin concentration was insufficient to counteract hyperglycemia as higher blood glucose levels were measured in rats with renal impairment, thus providing evidence of an insulin resistance evolution." (PMID 28459862, 2017). "In agreement with the results of the present study hyperglycemia blunted the benefits of insulin regarding infarct size, necrosis and apoptosis following myocardial ischemia/reperfusion." (PMID 28376800, 2017). "Previous studies have also demonstrated that GAG significantly ameliorates hyperglycemia, increases blood insulin levels, and improves the glucose tolerance through enhancing islet cell function." (PMID 28947964, 2017). "The effects of low-dose and high-dose corticosteroid therapies on mortality, LOS, drug costs and hyperglycaemia requiring insulin treatment were evaluated using propensity score analyses." (PMID 29284447, 2017). "Insulin omission is associated with frequent events of diabetic ketoacidosis, and DEB is linked with recurrent episodes of severe hyperglycemia and about one-third of individuals with T1D intentionally omit insulin." (PMID 28270369, 2017). "Despite the wide availability of medications and insulin coverage in Iran, the estimated national control of hyperglycemia, hyperlipidemia and hypertension (especially for young men and old women) remains subpar." (PMID 29044139, 2017). "Postprandial hyperglycemia is partially dependent of the rate of insulin secretion during postprandial period, which is believed to be associated with genic predisposition of T2D patients." (PMID 29089472, 2017). "Registered patients usually called when their blood glucose levels became uncontrolled or in any emergency like hypoglycemia, hyperglycemia, foot ulcer or to get adjustment in their regimen of oral medicine or insulin dose." (PMID 28811807, 2017). "It is possible that a transient postprandial hyperglycemia has been more prolonged in the insulin-treated mice than in those treated with Mo-LPI." (PMID 28208654, 2017). "Administering of insulin is preferable over reducing the glucose intake, unless hyperglycemia is excessive (>250 mg/dL) despite high insulin doses." (PMID 29308073, 2017). "DIO mice require high fat diets to become insulin resistant and glucose intolerant; however, these models develop only moderate hyperglycemia." (PMID 28640857, 2017). "This is consistent with previous findings that chronic hyperglycemia leads to a dramatic change in insulin to glucagon ratio and β-cell apoptosis in pancreatic islets." (PMID 28993702, 2017).
Hyperglycemia (continued). "This study demonstrated that CB0313.1 attenuates fasting hyperglycemia, improves insulin sensitivity by modifying the colonic microbial composition, and especially by increasing butyrate-producing bacteria, in T2D mice." (PMID 28765642, 2017). "Discontinuation of insulin infusion resulted in transient hyperglycaemia and significantly increased plasma levels of lipid oxidation products four weeks later, suggesting systemic lipid oxidation." (PMID 28421113, 2017). "It is characterized by impaired suppression of hepatic gluconeogenesis and glucose output by insulin, which plays a crucial role in the pathogenesis of hyperglycemia and glucose intolerance." (PMID 29404372, 2017). "In this model, over a 7 day period Ins-cMycERTAM Bcl-xL islet expansion is accompanied by reduced insulin expression in β cells with accompanying hyperglycemia." (PMID 28457793, 2017). "GPR40 activation with partial agonist MK-2305 leads to sustained reductions in hyperglycemia in the diabetic GK rat model accompanied by increases in glucose stimulated insulin secretion." (PMID 28542610, 2017). "Hyperglycemia, however, has been shown to result in disproportionate upregulation of hIAPP versus insulin, thus altering the ratio of hIAPP to insulin secreted by the β-cells." (PMID 28287098, 2017). "The hyperglycaemia stability of the FDF35 rats (85.5% insulin) together with their sensitivity to 3 different hypoglycaemic drugs strongly suggests their suitability as a non-genetic model of T2D." (PMID 28129400, 2017). "We have previously demonstrated reduced plasma levels of insulin and accompanying hyperglycaemia in R6/2 mice." (PMID 29066728, 2017). "Toxicities were expected to be manageable at the 0.4 mg/kg dose level with the use of short-acting insulin permitted to manage hyperglycemia, as reported in the first-in-human study." (PMID 27915408, 2017). "This downregulation is also in line with the fact that high plasma insulin and leptin levels are usually present concomitant with hyperglycaemia and high fat mass, respectively, that is, during periods of excess supply of nutrients." (PMID 28421113, 2017). "In conclusion, FAM3C is a new hepatokine that activates HSF1-CaM-Akt pathway to ameliorate hyperglycemia of type 1 diabetic mice by suppressing hepatic gluconeogenesis in an insulin-independent manner." (PMID 29285313, 2017). "Administration of a diet enriched with 10% cocoa for 9 weeks to Zucker diabetic fatty (ZDF) rats reduced hyperglycaemia, enhanced insulin sensitivity and increased β-cell mass and function." (PMID 29088075, 2017). "When GK rats are 28 days of age, basal hyperglycemia, impaired insulin secretion by pancreatic β-cells and increased hepatic glucose production are observed." (PMID 29220408, 2017). "On the other hand, the nitrite levels in high glucose exposed MS1 was increased as well and was decreased in insulin treated and β-mercaptoethanol supplemented group, which was to be expected as anti-hyperglycemia or anti-oxidant effects." (PMID 29213078, 2017). "Diabetic patients with liver failure receiving EN should be covered with long-acting isophane insulin suspension on a sliding scale for episodes of hyperglycemia." (PMID 29035319, 2017). "Hyperglycemia is defined as a state of excess glucose concentration in the blood, which develops when the body has too little insulin or when the body cannot use insulin properly." (PMID 27901482, 2017). "By reducing the chronic stimulation by hyperglycemia of β-cells to release insulin, low-dose ABA administration should improve survival and function of these cells." (PMID 28660193, 2017). "This is in good agreement with a previous study, which demonstrated that MBL-null mice were protected from myocardial injury after hyperglycemia and that they exhibited conditions similar to those of insulin-treated hyperglycemia mice." (PMID 28751823, 2017).
Hyperglycemia (continued). "Gluco-toxicity is a term used to convey the detrimental effect of hyperglycemia on β-cell function through impaired insulin synthesis." (PMID 28179377, 2017). "The adverse effects of hyperglycemia on insulin secretion have been clearly shown in animal models and human T2D, and although less thoroughly studied in T1D, it is becoming clear that similar beta cell changes take place with all forms of diabetes." (PMID 28174593, 2017). "These substances are phenolic compounds with important biological properties beyond antioxidant action; they also have insulin-sensitizing activities, reduce hyperglycemia via several mechanisms, and have a cardioprotective effect." (PMID 28584558, 2017). "Insulin levels in the circulating media during hyperglycaemia rose steadily in the co-cultures and reached a steady state once glucose levels had dropped to normoglycaemic levels." (PMID 29097671, 2017). "Hyperglycemia was stably maintained in diabetic animals by insertion of insulin pellets such that hyperglycemia was tightly controlled within the UNx STZ groups." (PMID 28434946, 2017). "The second physiological role of hypokalemia, with respect to endocrinology, is the impairment of both insulin release and end-organ sensitivity to insulin, resulting in hyperglycemia." (PMID 28264031, 2017). "Acarbose decreases the requirement for insulin by controlling postprandial hyperglycaemia and can reduce the blood glucose level after meals." (PMID 28219252, 2017). "Insulin therapy inhibits hyperglycemia, thus attenuates glucose-mediated inflammation, which suppresses pro-inflammatory cytokines and induces anti-inflammatory mediators." (PMID 28376867, 2017). "Pancreatic islet destruction by streptozotocin was reflected by the appearance of hyperglycaemia, which was corrected by subcutaneous implantation of insulin pellets." (PMID 28341857, 2017). "At the 40-hour time point, right before hyperglycemia emerged, pancreatic islet morphology was still intact and DT-treated islets stained positively for insulin, hence containing beta cells that contribute to the total BCM based on insulin staining." (PMID 28963457, 2017). "Usually babies with maternally inherited GCK-MODY and which have an increased set point stimulated insulin secretion, secrete a normal amount of insulin with maternal hyperglycemia, and have normal birth weights." (PMID 28663157, 2017). "T2D is characterized by a sustained hyperglycaemia due to the persistent damage in insulin secretion by pancreatic β-cell dysfunction and by insulin resistance at the peripheral tissues." (PMID 29088075, 2017). "Patients with T2D display postprandial hyperglycemia due to decreased insulin secretion and a concomitant increase in glucagon secretion." (PMID 29089472, 2017). "This disease model is characterized by moderate stable hyperglycemia, glucose intolerance, and reduced pancreatic insulin stores, and shares a number of syndromes with T2D patients." (PMID 29089569, 2017). "Infusion of glucose produced short (~20 min) lasting hyperglycemia (peak value = 203.9 ± 38.9 mg/dL) and elevations in insulin and C-peptide levels." (PMID 28261040, 2017). "Whereas ZDF obese rats displayed at the end of the study simultaneously hyperglycemia and hyperinsulinemia with Insulin levels of 3.4 ng/L, hyper-glycaemia with hypo-insulinemia was observed in STZ-injected Wistar rats." (PMID 28575111, 2017). "The DIAR-nSTZ mice had significantly higher blood glucose levels than the DIAR-control mice but the hyperglycemia improved significantly by insulin treatment." (PMID 28903776, 2017). "In T2DM patients, insulin sensitivity decreases in most organs and tissues, accompanied with symptoms like hyperglycemia, hyperlipidemia, hyperinsulinism, and so on." (PMID 29479370, 2017). "DM is mainly characterized by high blood glucose levels, i.e., hyperglycemia with altered metabolism of carbohydrates, proteins and fats due to reduced insulin secretions or/and insulin action." (PMID 29387011, 2017).
Hyperglycemia (continued). "In the presence of sepsis or septic lung injury, we encounter many patients who suffer from hyperglycemia due to increased insulin resistance." (PMID 29037205, 2017). "Recently, kinin receptor (B1 and B2) knockout mice showed age-related hyperglycemia, increases of hepatic gluconeogenesis, intolerance of glucose, decreases in insulin sensibility, and functional impairment of pancreatic islets." (PMID 28902927, 2017). "It has long been known that a diet high in carbohydrate elevates postprandial hyperglycemia and insulin responses, together accelerating the progression of T2D and atherosclerotic CVD." (PMID 29075629, 2017). "It is generally understood that hyperglycaemia acts on endothelial cell function and resultant microvascular endothelial dysfunction perpetuates a cycle with a reduction in insulin-mediated glucose uptake." (PMID 28915818, 2017). "In mice with STZ-induced T2DM, intravenous infusion of allogeneic BM-MSCs resulted in the appearance of considerable insulin/glucagon double hormone-positive cells followed by restoration of beta-cell mass and dramatic amelioration of hyperglycemia." (PMID 28515792, 2017). "In preclinical animal studies, controlling hyperglycemia with insulin resulted in heterogeneous neuroprotection outcomes." (PMID 28168113, 2017). "In some critical illnesses, intensive insulin therapy is utilized to combat the harmful effects of hyperglycemia." (PMID 29069833, 2017). "Fasting to postprandial transition requires a tight adjustment of insulin secretion to its demand, so tissue (e.g., skeletal muscle) glucose supply is assured while hypo-/hyperglycemia are prevented." (PMID 28286777, 2017). "The result of the present study indicates that acute hyperglycemia blunts the cardioprotective effects of pre-ischemic insulin pre-conditioning most likely mediated by the impairment of Akt activation." (PMID 28376800, 2017). "In contrast, another study indicated that intramuscular administration of volatile oil of RE (25 mg/kg) for 30, 60 and 120 min inhibited insulin release and increased blood glucose levels leading to hyperglycemia in normal and alloxan-induced diabetic rabbits." (PMID 28862678, 2017). "Toward this goal, we combined the ASL-fMRI with peripheral sampling of glucose, insulin and C-peptide to map the transition from fasting glycemia to hyperglycemia." (PMID 28261040, 2017). "During follow-up, subcutaneous insulin doses needed to be increased in order to avoid hyperglycemia." (PMID 28044993, 2017). "Regarding treatment of hyperglycaemia, the majority, 68.1% of the study patients were on oral agents only and 12.0% were using combined oral agents with insulin." (PMID 29191193, 2017). "Doses of GI at glucose (2 g/kg) and insulin (1 unit/3 g glucose) were determined, because higher doses of glucose (4 or 8 g/kg) resulted in serious hyperglycemia." (PMID 28978999, 2017). "Myriocin treatment noticeably improved glucose metabolism via reduction of hyperglycemia together with improvements in insulin levels and HOMA index." (PMID 29234684, 2017). "Chronic exposure to hyperglycemia can lead to glucotoxicity that pertains to the dysfunction of pancreatic β-cell characterized by decreasing insulin gene expression with and accelerated apoptosis." (PMID 28230764, 2017). "In people with hyperglycemia, β cell role is gradually deviated; glucose-induced insulin secretion becomes damaged along with β cells' degranulation; a reduction of β cells quantity sometimes also occurs." (PMID 28424779, 2017). "DM is a metabolic disorder of the endocrine system, and it is characterized by hyperglycemia resulting in an increased hepatic glucose production, diminished insulin secretion, and impaired insulin action." (PMID 28758125, 2017). "The SREBP-1c is an insulin-dependent molecule that regulates de novo lipogenesis.The positive regulation on the SREBP-1c can directly regulates hyperglycemia and fatty acid synthesis via insulin signaling." (PMID 28885559, 2017).